IL17RA (interleukin 17 receptor A)
Diseases named in the same sentence as IL17RA in open-access papers (continued):
Sharing a sentence is not in itself a finding about the gene and the disease.
parasitemia (2 papers, 2012 to 2018). "As expected due to the role of this cytokine in parasite control, IFN-γ blockade during T. cruzi infection resulted in higher parasitemia in WT and IL-17RA KO mice after 20 days post-infection." (PMID 22577359, 2012). "Neutrophil adoptive transfer resulted in a significant drop in the parasitemia levels in both infected WT and IL-17RA KO mice." (PMID 22577359, 2012). "In addition, histological data from these initial studies suggested that infected IL-17RA knockout (KO) mice exhibited increased parasite levels in tissues, but similar levels of parasitemia, compared with those of their infected wildtype (WT) counterparts." (PMID 30364284, 2018). "Thus, repetitive adoptive transfer of neutrophils during T. cruzi infection resulted in lower parasitemia in both WT and IL-17RA KO mice and in reduced IFN-γ production only in WT mice." (PMID 22577359, 2012). "Specific depletion of Ly-6G+ neutrophils in vivo during T. cruzi infection raised parasitemia and serum IFN-γ concentration and resulted in increased liver pathology in WT mice and overwhelming wasting disease in IL-17RA KO mice." (PMID 22577359, 2012). "Remarkably, the transfer of IL-17RA-sufficient WT CD8+ T cells, but not of IL-17RA-deficient KO CD8+ T cells, was able to enhance parasite control and significantly reduce parasitemia." (PMID 30364284, 2018). "Interestingly, the reduction of parasitemia levels after neutrophil transfer was not enough to prevent mortality as neutrophil-injected IL-17RA KO mice showed the same mortality than the control KO group." (PMID 22577359, 2012).
skin tumors (2 papers, 2012 to 2022). "Il17ra(T779A)-KI significantly reduced tumor incidence, and Il17rc-KO completely prevented the development of skin tumors, which supports the view that IL17 signaling promotes tumorigenesis." (PMID 36009523, 2022).
synovitis (2 papers, 2017 to 2025). Inflammation of a synovial membrane. "In an OA mouse model, inhibition of IL-6 through IL-17RA-mediated pathways was found to suppress synovitis." (PMID 40589764, 2025).
acute peritonitis (1 paper, 2014). "Peritoneal macrophage accumulation and CD11c expression in acute peritonitis were decreased in IL-17 and IL-17 receptor A deficient (Il17ra-/-) mice." (PMID 24454873, 2014).
arteritis (1 paper, 2024). An inflammatory process affecting an artery. "It still needs further investigation to elucidate whether IL-17F contributes much less than IL-17A in mediating IL-17RA-downstream cascades for leukocyte recruitment and aortic inflammation in our model and KD-related arteritis." (PMID 38451335, 2024). "Il17ra-deficiency mice developed less LCWE-induced arteritis with fewer neutrophil infiltration, absent aortic IL-17RA augmentation, and less early Inos and Cxcl1 upregulations." (PMID 38451335, 2024).
arthropathy (1 paper, 2022). Any disorder of the joints. "Interestingly, CD4+ and CD8+ T cells in the feet during the acute phase of disease expressed both IL-17A and IL-17F, indicating that IL-17RA signaling may require binding of both IL-17A and IL-17F isoforms in the context of alphavirus-induced arthropathy." (PMID 35143591, 2022).
atopic asthma (1 paper, 2021). An asthma that is characterized by symptoms that are triggered by an allergic reaction caused by inhaled allergens such as dust mite allergen, pet dander, pollen and mold. "The expression of IL-17RB and IL-17RA on eosinophils were found to be significantly higher in patients with atopic asthma." (PMID 34301307, 2021).
bone marrow failure (1 paper, 2020). "This includes genes mutated in rare hematological syndromes (ADA, GP6, IL17RA, PRF1, and SEC23B), reported in prior MDS/AML or inherited bone marrow failure (IBMF) series (DNAH9, SH2B3, and NAPRT1), or novel loci where loss-of- function of the identified germline variants was demonstrated (DHX34)." (PMID 32098966, 2020).
brain injuries (1 paper, 2019). "It has been reported that interleukin‐17A and IL‐17A receptor IL‐17RA/(C/EBPβ)/SIRT1 signaling pathway enhances reactive astrogliosis after brain injuries." (PMID 31020769, 2019).
brain tumors (1 paper, 2024). "Our analysis showed that IL-17RA protein levels were significantly higher in brain tumors and uterine tumors than in the corresponding normal control tissues." (PMID 38672111, 2024).
chronic hepatitis (1 paper, 2022). An active inflammatory process affecting the liver for more than six months. "Furthermore, in both murine chronic hepatitis models induced by HFD or chemicals, we demonstrated that overexpression of FTO facilitates the liver injury and inflammation via induction of IL-17RA." (PMID 36172147, 2022).
chronic lung disease (1 paper, 2022). According to the definitions of the American and British Thoracic Societies, including pulmonary functional tests, X-rays, and CT scans for items such as fibrosis, bronchiectasis, bullae, emphysema, nodular or lymphomatous abnormalities. "The IL-17A/IL-17RA axis has been reported to participate in several acute and chronic lung diseases." (PMID 36411467, 2022).
co-infection (1 paper, 2023). "Given that the NP niche is a primary site of bacterial-viral interactions, our results suggest that IL-17RA-mediated epithelial injury can allow commensal bacterial colonization to develop in invasive infection during Spn-IAV co-infection." (PMID 38060620, 2023).
cutaneous candidiasis (1 paper, 2015). Candidiasis of the skin manifested as eczema-like lesions of the interdigital spaces, perleche, or chronic paronychia. "The similarities between WT littermate controls and IL-17RE-/- mice indicate that IL-17C signaling via IL-17RE is not essential for protection from or the resolution of cutaneous candidiasis, whereas IL-17A signaling through IL-17RA/IL-17RC is nonredundant." (PMID 25849644, 2015).
cystitis (1 paper, 2016). Inflammation of the urinary bladder. "We also observed that there were more neutrophils in cystitis tissue than polyp and cancer, accompanied with increased IL-17RA, IL-17E and IL-17RB expression." (PMID 27716046, 2016).
dysplasia (1 paper, 2024). A usually neoplastic transformation of the cell, associated with altered architectural tissue patterns. "All H. pylori infected Il17ra-/- mice developed dysplasia or cancer and the H. pylori infected wild type mice only developed gastritis." (PMID 39588838, 2024).
gastric disease (1 paper, 2024). "Our data suggest a link between Cybb expression, chronic inflammation, and gastric disease outcomes in the IL-17RA deficient InsGAS mice." (PMID 39588838, 2024).
gastritis (1 paper, 2024). Inflammation of the stomach. "Six weeks post-infection, IL-17RA deficiency led to increased bacterial burden, increased gastritis, and development of lymphoid follicles." (PMID 39588838, 2024). "Representative H&Es are presented with normal mucosa (WT), mild gastritis (WT) and low-grade dysplasia (Il17ra-/-)." (PMID 39588838, 2024). "Our research using the Cre-flox model, Foxa3creIl17rafl/fl, suggests that loss of IL-17RA on epithelial cells but not fibroblasts does lead to increased gastritis, but the impact is not as dramatic as a germline mutation in Il17ra." (PMID 39588838, 2024).
glomerulonephritis (1 paper, 2020). A renal disorder characterized by damage in the glomeruli. "By using Fcgr2b-/- mice that were also deficient in Act1, a crucial adaptor molecule downstream from the IL-17RA/IL-17RC complex, it was shown that IL-17A deletion significantly reduced inflammatory monocyte and neutrophil infiltration and thus the severity of glomerulonephritis." (PMID 32059488, 2020).
H1N1 virus infection (1 paper, 2019). "However, previous studies of IL-17RA-deficient mice reported that IL-17 may act as a double-edged sword by contributing to pulmonary immunopathology in pandemic H1N1 virus infection." (PMID 31681209, 2019).
head and neck squamous cell carcinoma (1 paper, 2022). A squamous cell carcinoma that arises from any of the following anatomic sites: lip and oral cavity, nasal cavity, paranasal sinuses, pharynx, larynx, and salivary glands. "Moreover, gene expression analyses using the TCGA database showed that IL-17RA mRNA levels were significantly higher in head and neck squamous cell carcinoma (HNSC) tissues than in the corresponding normal tissues." (PMID 36000726, 2022).
helminth infections (1 paper, 2022). "Although there is scarce data related to IL-17/IL-17RA axis in toxocariasis in the literature, studies relating IL-17 to helminth infections have expanded." (PMID 35844540, 2022).
hyper-IgE syndrome (1 paper, 2015). A condition that is characterized by elevated serum IgE, dermatitis, and respiratory infections. "The importance of the IL-17R pathway has been observed not only in knockout mouse models, but also in humans with rare genetic mutations that impact generation of Th17 cells or the IL-17 signaling pathway, including Hyper-IgE Syndrome (STAT3 or TYK2 mutations) or IL17RA or ACT1 gene deficiency." (PMID 25849644, 2015).
ischemia (1 paper, 2022). A hypoperfusion of the BLOOD through an organ or tissue caused by a PATHOLOGIC CONSTRICTION or obstruction of its BLOOD VESSELS, or an absence of BLOOD CIRCULATION. "Besides, IL-1R2-overexpressed mice reduced the expressions of p-STAT1, IL-17RA, Bax, and in heart from mice with 45 min of ischemia followed by 3 h of reperfusion." (PMID 35087030, 2022).
leukemia (1 paper, 2024). A malignant (clonal) hematologic disorder, involving hematopoietic stem cells and characterized by the presence of primitive or atypical myeloid or lymphoid cells in the bone marrow and the blood. "We then conducted GSEA to compare patients with leukemia with IL-17RA mRNA expression (205707_at) above the median level (IL-17RA high) with patients with leukemia with IL-17RA mRNA expression below the median level (IL-17RA low)." (PMID 38172124, 2024). "Considering that leukemia cells acted mainly as responders but did not release IL-17A, IL-17RA, the receptor for IL-17A, should be a better marker of leukemia cells responding to IL-17A stimulation." (PMID 38172124, 2024).
mastitis (1 paper, 2026). Inflammation of breast tissue during lactation or postpartum due to an obstructed duct or infection. "Notably, network pharmacology screening combined with molecular dynamics simulations revealed stable binding of baicalin to IL-17RA, suggesting that baicalin exerts its protective effect to alleviate mastitis by targeting IL-17RA." (PMID 41987311, 2026).
Myocardial fibrosis (1 paper, 2013). "The IL-17 receptor (IL-17R, mainly IL-17RA) is expressed in the heart tissue fibroblasts, and myocardial fibrosis is a key factor in the series of pathologic reactions that occur during the progression of myocarditis to DCM." (PMID 23977238, 2013).
ocular infection (1 paper, 2023). "Upon ocular infection of IL-17RA-/- and IL-17RC-/- mice with HSV-IL-2, demyelination was detected in all samples of both IL-17RA-/- and IL-17RC-/- infected mice." (PMID 36817487, 2023).
oral diseases (1 paper, 2021). "Since both IL-1α and IL-1β are implicated in the pathology of OM, and IL-1α at least partially regulates neutrophils in other oral diseases, we asked if blocking IL-1R in WT and Il17ra−/− mice would account for the increased damage when IL-17RA is lacking." (PMID 34220843, 2021).
osteomyelitis (1 paper, 2022). An acute or chronic inflammation of the bone and its structures due to infection with pyogenic bacteria. "The expression of 2 interleukin-related genes were significantly different, among which IL11RA and IL17RA were highly expressed in gene cluster B osteomyelitis." (PMID 36544487, 2022). "The expression of 2 interleukin-related genes was significantly different, with IL11RA and IL17RA highly expressed in cluster B osteomyelitis." (PMID 36544487, 2022). "The differences between IL11RA and IL17RA in the m6A cluster and gene cluster suggested that the two genes may be involved in osteomyelitis-mediated inflammation." (PMID 36544487, 2022).
osteoporosis (1 paper, 2023). A condition of reduced bone mass, with decreased cortical thickness and a decrease in the number and size of the trabeculae of cancellous bone (but normal chemical composition), resulting in increased fracture incidence. "The Area Under Curve (AUC) was 0.802, suggesting a high diagnostic value and potential of IL17RA as a diagnostic marker for osteoporosis." (PMID 37600656, 2023). "In conclusion, we identified the immune-related gene IL17RA as a diagnostic marker of osteoporosis by elucidating its biological function within the immune system." (PMID 37600656, 2023). "Then, we constructed a protein–protein interaction (PPI) network to identify hub genes, and finally determined the immune-related gene IL17RA as a potential biomarker for osteoporosis after validating it in another dataset (GSE35959)." (PMID 37600656, 2023). "To investigate the functions of IL17RA in osteoporosis, we conducted Gene Set Enrichment Analysis (GSEA) by stratifying samples based on IL17RA expression." (PMID 37600656, 2023). "The IHC results showed that IL17RA expression was higher in the severe osteoporosis group compared to the mild osteoporosis group." (PMID 37600656, 2023). "This also shows that the role of IL17RA in osteoporosis is still controversial, and an increased sample size is needed for an in-depth analysis." (PMID 37600656, 2023). "RT-qPCR and immunohistochemical results showed that the expression of IL17RA was significantly higher in osteoporosis patients compared to the normal group, as evidenced by the area under the curve Area Under Curve of 0.802." (PMID 37600656, 2023). "RT-qPCR results showed that mRNA expression levels of IL17RA were significantly higher in peripheral blood of patients with osteoporosis compared to those of patients in the control group (p < 0.05)." (PMID 37600656, 2023). "Finally, functional enrichment analysis revealed that IL17RA was involved in the development and progression of osteoporosis by regulating local immune and inflammatory processes in bone tissue." (PMID 37600656, 2023). "We identified hsa-miR-128-3p as a key regulatory miRNA for IL17RA in osteoporosis." (PMID 37600656, 2023). "Secondly, although we validated the diagnostic value of IL17RA using patients’ peripheral blood samples and bone tissues, the sample size of this study was also limited, and the clinical translational value of IL17RA needs to be validated in a larger number of clinical osteoporosis samples." (PMID 37600656, 2023). "We constructed the NEAT1-hsa-miR-128-3p-IL17RA and SNHG1-hsa-miR-128-3p-IL17RA networks to provide a theoretical basis for understanding the molecular mechanisms of IL17RA involvement in osteoporosis." (PMID 37600656, 2023).
papilloma (1 paper, 2022). A benign epithelial neoplasm that projects above the surrounding epithelial surface and consists of villous or arborescent outgrowths of fibrovascular stroma. "In the skin papilloma model, Il17ra(T779A)-KI significantly decreased tumor burden compared to the WT, while Il17rc-KO abolished papilloma development." (PMID 36009523, 2022).
pemphigus (1 paper, 2024). Pemphigus is a group of rare autoimmune diseases that cause blistering of the skin and mucous membranes (mouth, nose, throat, eyes, and genitals).This conditioncan occur at any age, but often strikes people in middle or older age. "In line with previous human pemphigus studies, the data presented here confirm the overexpression of IL-17A, IL-17F, IL-17RA, IL-23A, and IL-23R in canine PF skin." (PMID 38393106, 2024).
pneumococcal infection (1 paper, 2018). Infections with bacteria of the species streptococcus pneumoniae. "As observed with the other pneumococcal infections, blood neutrophils were significantly reduced in the Il17ra KO animals after infection." (PMID 29813133, 2018).
pneumococcal pneumonia (1 paper, 2018). A febrile disease caused by STREPTOCOCCUS PNEUMONIAE. "To address this issue, we have utilized a murine model of pneumococcal pneumonia in which the gene for the IL-17 cytokine family receptor, Il17ra, has been inactivated." (PMID 29813133, 2018).
Q fever (1 paper, 2020). A bacterial infection caused by Coxiella burnetii. "Preliminary data from our team show that peripheral blood mononuclear cells from patients with persistent Q fever produce less IL-17 and IL-17RA compared to patients with acute Q fever (unpublished data)." (PMID 32765448, 2020).
Salmonella Infections (1 paper, 2022). Infections with bacteria of the genus SALMONELLA. "It has also been reported that chicken IL-17RA expression remains unchanged in Salmonella infection." (PMID 35923229, 2022).
schizophrenia (1 paper, 2021). A major psychotic disorder characterized by abnormalities in the perception or expression of reality. "By diagnosis, there was a trend toward an increase of IL1A mRNA in schizophrenia cases (t = −1.731, df = 52, p = 0.089) and IL17RA mRNA was significantly increased in schizophrenia cases compared with control subjects (t = −3.952, df = 54, p < 0.001) (data not shown)." (PMID 31168068, 2021).
skin infection (1 paper, 2023). An inflammatory process affecting the skin, caused by bacteria, viruses, parasites, or fungi. "This role of DETCs was only revealed in mice lacking IL17RA, but not in WT mice, which is consistent with the lack of observed susceptibility to S. aureus skin infection in Ets1 KO animals." (PMID 37691956, 2023).
skin papilloma (1 paper, 2022). A benign papillary neoplastic growth on the skin composed of epithelial cells and a fibrous stalk. "During the 13-week monitoring of the mice for skin tumorigenesis, the formation of skin papilloma in WT mice occurred 1 week earlier than in the Il17ra(T779A)-KI mice." (PMID 36009523, 2022).
Splenomegaly (1 paper, 2019). Abnormal increased size of the spleen. "IL-17RA KO/lpr mice presented with significantly enhanced lymphoproliferation compared with B6/lpr mice, which was characterized by dramatic lymphadenomegaly/splenomegaly and increased lymphocyte numbers, expansion of double-negative (DN) T-cells and enhanced plasma cell formation." (PMID 30858513, 2019).
staphylococcal infection (1 paper, 2023). An infection caused by Staphylococcus. "To probe the mechanistic role of DETC in staphylococcal infection, we depleted DETCs from IL17RA KO mice, which led to enhanced susceptibility to skin staphylococcal infections." (PMID 37691956, 2023).
status epilepticus (1 paper, 2019). Status epilepticus is defined as a continuous seizure lasting more than 30 min, or two or more seizures without full recovery of consciousness between any of them. "A recent study using the kainic acid mouse model of status epilepticus found a direct effect of IL-17 on neuronal excitability and cell viability, as well as delayed seizure onset in IL-17RA–deficient mice." (PMID 30912766, 2019).
steatosis (1 paper, 2016). Increased lipid within the cytoplasm of cells. "Further, we show that deficiency of IL-17A, IL-17F or IL-17RA results in increased steatosis, but reduced steatohepatitis when fed MCDD." (PMID 26895034, 2016). "In contrast, IL-17RA-/-, IL-17A-/-, and IL-17F-/- mice, despite increased steatosis, exhibited significant protection from hepatocellular damage compared to WT controls." (PMID 26895034, 2016).
systemic sclerosis (1 paper, 2023). A chronic disorder, possibly autoimmune, marked by excessive production of collagen which results in hardening and thickening of body tissues. "A strong association between inflammatory cytokines and capillary abnormalities is suggested by the reported efficacy of brodalumab, an anti-IL-17RA antibody, in the treatment of systemic sclerosis, one of the most common diseases showing nailfold capillary abnormalities." (PMID 37928519, 2023).